TGFB1 (transforming growth factor beta 1)
Diseases named in the same sentence as TGFB1 in open-access papers (continued):
Sharing a sentence is not in itself a finding about the gene and the disease.
renal fibrosis (continued). "Our recent studies have shown that blockade of HDAC6 with ACY-1215 also attenuated renal fibrosis through a mechanism involving the inactivation of TGFβ1/Smad3, EGFR/AKT, STAT3 and NF-κB signaling pathways in a murine model of UUO injury." (PMID 35559244, 2022). "In a TGFβ1-or UUO-induced renal fibrosis model, overexpression of phosphatase and tensin homolog deleted on chromosome ten (PTEN) inhibits the FAK signaling pathway." (PMID 35359592, 2022). "Protein kinase Cα (PKCα) is one of the major subpathways of mTORC2, and the Rictor/mTORC2 signaling pathway is involved in TGFβ1-induced fibroblast activation and renal fibrosis." (PMID 36105212, 2022). "Another encouraging fact is that secreted Klotho was able to inhibit TGFβ1 signaling by binding to the type-II TGFβ receptor inhibiting TGFβ1 binding to cell surface receptors, thus suppressing the renal fibrosis development." (PMID 34065339, 2021). "In the process of renal fibrosis, macrophages not only act as immune cells, but also directly transform into myofibroblasts in the damaged kidney mediated by the TGFβ1/SMAD3 pathway, via a process known as macrophage-to-myofibroblast transition (MMT)." (PMID 34776968, 2021). "It has been shown that AS.IV suppresses TGFβ1 induced renal fibrosis by inhibiting NF-kB activation." (PMID 34830390, 2021). "Exosomes carried Transforming Growth Factor Beta 1 (TGF-β1) mRNA derived from glomerular endothelial cells (GECs) that activate mesangial cells to promote renal fibrosis in DN." (PMID 34977033, 2021). "Transforming growth factor beta 1(TGFB1 or TGF-β1) is a critical profibrotic factor in renal fibrosis." (PMID 34093596, 2021). "In the cited experiment, adding liraglutide ameliorated the expression and accumulation of all measured biomarkers of renal fibrosis; liraglutide directly inhibited the action of TGFβ, inhibiting expression of both TGFβ1 and TGFβ1 receptor." (PMID 34639160, 2021). "Transforming growth factor-beta 1 (TGF-β1) signalling is thought to be a convergent pathway which mediates the progression of renal fibrosis in CKD." (PMID 33375963, 2021). "Several studies have focused on the inhibition of TGFβ1 and its downstream molecules for the treatment of renal fibrosis." (PMID 34645813, 2021). "In contrast, in Klf5+/– UUO‐mice, the expression of fn1 and tgfβ1 gene which encode for FN and TGF‐β were increased concurrent with increased renal fibrosis as compared to UUO‐WT mice." (PMID 33523554, 2021). "One of the factors that play an important role in renal fibrosis is TGFβ1 which is considered the key driver of renal fibrosis." (PMID 33654066, 2021). "In this work, we demonstrate that renal fibrosis after experimental UPEC pyelonephritis is driven by TGFβ1 and enhanced by androgens." (PMID 32227630, 2020). "These cells secrete a number of cytokines and chemokines involved in immunomodulation and repair, including TGFβ1, a chief signaling factor in renal fibrosis." (PMID 32849562, 2020). "For instance, curcumin (200 mg/kg) can improve renal fibrosis during cisplatin chemotherapy downregulation of transforming growth factor-beta 1 (TGF-β1)." (PMID 33187385, 2020). "Metformin attenuated TGFβ1 expression in renal tissues from a folic acid-induced rat model of renal fibrosis and a UUO mouse model." (PMID 32364526, 2020). "Investigating the underlying molecular mechanisms, we found a decreased expression of Tgfb1, Pdgfb and Ctgf, the core factors of renal fibrosis in the kidneys of Il20rb KO compared to WT mice after UUO." (PMID 32306980, 2020). "High glucose-induced ROS generation play a central role in extracellular matrix synthesis via up-regulation of pro-fibrotic factors like TGFβ1 and angiotensin II, leading to renal fibrosis." (PMID 31590361, 2019).
renal fibrosis (continued). "The positive control resveratrol was also shown to inhibit renal fibrosis through the TGFβ1/Smads pathway, supporting the present study." (PMID 31531112, 2019). "Currently, only one study on transforming growth factor beta-1 (TGF-β1)-induced renal fibrosis found that LXA4 attenuated the expression of the Notch ligand Jagged1 (JAG1) and downstream molecule Hes1." (PMID 30778288, 2019). "Urinary transforming growth factor beta 1 (TGF-β1) is considered the most popular mediator for detecting the severity of renal fibrosis in cats." (PMID 30744640, 2019). "Amongst these, TGFβ1 plays a key role in the development of renal fibrosis and was reduced at the protein level in both MASP-2−/− and HG4 treated mice with proteinuria." (PMID 31608060, 2019). "Elevated TGFβ1 and downstream Smad3 and Smad2 in the kidney activate profibrotic genes and mediate renal fibrosis." (PMID 31531112, 2019). "In the pathogenesis of renal fibrosis, transforming growth factor beta-1 (TGF-β1) plays a major role, since it directly promotes the fibroblast proliferation and stimulates their collagen synthesis." (PMID 31828127, 2019). "TGFβ1 is a central cytokine in renal fibrosis and has multiple functions in renal inflammation and apoptosis." (PMID 28409163, 2017). "In conclusion, BZM directly inhibits renal fibrosis in CKD via suppression of TGFβ1-Smad3 signaling and is promising in terms of drug repositioning." (PMID 29026167, 2017). "TGFβ1 is a central cytokine in the regulation of renal fibrosis in various models, which initiates fibrosis via the activation of the Smad3 signaling pathway." (PMID 27732564, 2016). "Atorvastatin pretreatment and delayed treatment shared similar efficacy in attenuating TGFβ1 expression, leading to renal fibrosis reduction compared to that seen in the gentamicin-treated rats (P < 0.05)." (PMID 27727327, 2016). "The expression of TGFβ1, a key mediator of renal fibrosis, in renal cortical tissues, was significantly increased in the gentamicin group when compared to that of the control and atorvastatin groups (P < 0.05)." (PMID 27727327, 2016). "This interaction between DDR1 and TGFβ1-Smad3 signaling can explain, at least partly, the decreased progression of renal fibrosis after the inhibition of DDR1 expression in the antisense groups." (PMID 26880216, 2016). "Transforming growth factor-beta 1 (TGF-β1) is an important regulator of renal fibrosis and TGF-β1 gene activation, while its corresponding signaling protein Smad plays an important role in fibrosis in other organs and tissues." (PMID 26451157, 2015). "Ureter obstruction resulted in a large increase in renal fibrosis and macrophage infiltration markers (TGFβ1, COL1A1, and F4/80), which were unaffected by either CD40 activation or in CD40 knockout mice." (PMID 26623936, 2015). "et Zuce), was found to efficiently decrease expression of renal fibrosis marker transforming growth factor beta 1 and matrices in DKD rats." (PMID 25938778, 2015). "The results of this study indicated that there were significant differences between the urinary TGFβ1 levels of LN cases with renal fibrosis and those of the control group." (PMID 25279306, 2014). "Various mediators of renal fibrosis have been described, such as the prototypical profibrotic molecules transforming growth factor beta 1 (TGF-β1) and platelet-derived growth factor (PDGF), which will not be discussed in detail here." (PMID 24678881, 2014). "Our results indicated that T869C gene polymorphism of TGFβ1 changes the signal peptide, that contributes to the production of urinary TGFβ1 and affects renal fibrosis in lupus nephritis." (PMID 25279306, 2014). "In contrast, overexpression of EP2 significantly increased the production of cAMP, suggesting that although activation of EP2 receptor cannot entirely inhibit TGFβ1 induced renal fibrosis, it can decrease cell damage via up-regulation of the cAMP levels." (PMID 25327961, 2014).
renal fibrosis (continued). "All lupus patients underwent renal biopsy to assess their protein expression of TGFβ1 in the renal tissue by immunohistochemistry and their renal fibrosis by morphometry and chronicity index." (PMID 25279306, 2014). "Further analysis showed that TGFβ1 levels had a positive correlation with chronicity index scores (r = 0.606; p <0.05), renal fibrosis (r = 0.602; p <0.05) and protein expression of TGFβ1 in renal tissue (r =0.660; p <0.05)." (PMID 25279306, 2014). "The observations of the present study indicate that saponin suppressed the gene expression of TGFB1 in the renal samples of the SHRs allowing it to inhibit TGFB1-mediated pathways therefore leading them towards renal fibrosis." (PMID 23404227, 2013). "RA has been shown to promote cell survival and antagonize renal fibrosis in models of glomerular injury, while administration of isotretinoin (13-cis-RA) or all-trans RA attenuates interstitial fibrosis and reduces TGFβ1 expression in UUO." (PMID 24023768, 2013). "Accordingly, BMP-7 has also been reported to inhibit many processes involving TGFβ1 including renal fibrosis, cardiac fibrosis and allograft rejection in vivo as well as EMT and at high concentrations, endothelial cell-mesenchymal transition." (PMID 19112509, 2008). "BMP-7 has been reported to inhibit renal fibrosis and TGFβ1-induced epithelial-mesenchymal transition (EMT), in part through negative interactions with TGFβ1 induced Smad 2/3 activation." (PMID 19112509, 2008). "Based on these observations, we hypothesized that Gal3 promotes renal fibrosis through regulating the TGFβ1 signaling pathway." (PMID 40799164, 2025). "TGFβ1 is thought to be the master regulator of renal fibrosis, particularly in CKD52." (PMID 41390888, 2025). "Similarly, Renshen Guben oral liquid (RSGB), a formula approved by the National Medical Products Administration (NMPA) of China, has been shown to mitigate renal fibrosis via the TGFβ1/Smad2/3, Wnt4/β-catenin, and NGFR/NF-κB pathways." (PMID 41333019, 2025). "Transforming growth factor-beta-1 (TGF-β1) emerges as a primary initiator of renal fibrosis." (PMID 39687299, 2024). "Previous studies have shown that macrophage-derived TGFβ1 promotes renal fibrosis." (PMID 38594728, 2024). "Furthermore, the activation of NRF2 ameliorated renal fibrosis in HN mice through the downregulation of the transforming growth factor-beta 1 (TGF-β1) signaling pathway and ultimately delayed the progression of HN." (PMID 37237889, 2023). "Our results, for the first time, provide evidence that activating NRF2 improves mitochondrial homeostasis by reducing oxidative stress and upregulating antioxidant signaling pathways ultimately alleviates renal fibrosis by downregulating transforming growth factor-beta 1 (TGF-β1) signaling pathways." (PMID 37237889, 2023). "In conclusion, FXR may be involved in the development of renal fibrosis in DN through the regulation of the TGFβ1-Smad signaling pathway in vitro." (PMID 37790634, 2023). "However, the importance of actA as a mediator of TGFβ1-induced renal fibrosis was apparent after induction of renal injury with UUO." (PMID 36717814, 2023). "However, due to the side‐effects of TGFβ inhibition in autoimmune diseases, direct targeting of TGFβ1 is barely possible to be a viable strategy against renal fibrosis and DN." (PMID 37303813, 2023). "FXR may negatively regulate TGFβ1 expression and restore the balance of the TGFβ1-Smad signaling pathway to ameliorate renal fibrosis." (PMID 37790634, 2023). "To further clarify the mechanism of ecliptasaponin A in attenuating renal fibrosis, we performed transcriptome sequencing of HK-2 cells treated with TGFβ1 and ecliptasaponin A. The functions and pathways were mainly enriched in the extracellular matrix and TGFβ signalling pathway." (PMID 37831322, 2023). "SZ-A also improved renal fibrosis by lowering the expression of TGFβ1 in the kidneys." (PMID 37359004, 2023).
renal fibrosis (continued). "Moreover, the expression of TGFβ1 and αSMA, which reflect renal fibrosis, was significantly increased." (PMID 36928344, 2023). "In addition, ROS can activate pro-inflammatory and pro-fibrotic pathways, such as nuclear factor NF-κB, and favor renal fibrosis by increasing TGFβ1 expression." (PMID 36830953, 2023). "In conclusion, our study, for the first time, identified the chemical constituents in RSGB by UPLC-QTOF-MS/MS and demonstrate that the improvement of renal fibrosis by RSGB is related to the inhibition of Tgfβ1/Smad2/3 pathway, Wnt4/β-catenin pathway and NGFR/NF-κB pathway." (PMID 37198665, 2023). "Ang II also stimulates renal fibrosis in a TGFβ1 signaling-independent manner." (PMID 35629404, 2022). "Therefore, regulation of the Sirtuin family in DKD via TGFβ1 is mainly related to extracellular matrix accumulation at the early stage leading to renal fibrosis." (PMID 35774140, 2022). "Furthermore, latent TGFβ1 is known to protect from renal fibrosis and inflammation and to suppress T-cell proliferation and activation through Treg differentiation." (PMID 35628410, 2022). "Dysregulation of TGFβ signalling is implicated in several diseases and inflammatory pathologies; notably in the context of renal fibrosis, TGFβ1 plays a central role as a pro-fibrotic factor and is pivotal for driving the development and progression of end-stage renal disease." (PMID 36435939, 2022). "Moreover, urine stem cell-derived EXOs loaded with miR-145 and miR-320c induced renal fibrosis through activation of TGFβ1 expression." (PMID 36363614, 2022). "A recent study showed that c-Jun could be progressively elevated, and it could activate the expression of TGFβ1 via ross-activation and autoregulation during renal fibrosis in DN." (PMID 34552655, 2021). "In another study, rats that underwent 5/6 nephrectomy showed that rutin administration for 20 weeks decreased renal fibrosis and reduced proteinuria, the authors of the study related these effects of rutin to its antioxidant properties and the suppression of the TGFβ1-Smad signaling pathway." (PMID 35052518, 2021). "TGFβ1 is the master player in tissue fibrosis including renal fibrosis." (PMID 34867480, 2021). "On this basis, an alternative explanation for our findings is that JMJD3 inhibition-mediated upregulation of TGFβ1 and activation of Smad3 strengthens activation of Notch signaling, which in turn, further activates TGFβ1 signaling, creating a vicious circle that accelerates renal fibrosis." (PMID 33456568, 2021). "In the present study, by using a unilateral ureteric obstruction (UUO)-induced mouse model of renal fibrosis, and culturing renal TECs exposed to TGFB1, we demonstrated that PARK7 protects against renal TIF and related kidney injury by inducing SOD2 and scavenging ROS." (PMID 34093596, 2021). "It is therefore possible that the administration of a TGFβ1 inhibitor to patients with LN may reduce the deposition of immune complexes, the inflammatory response, and renal fibrosis." (PMID 34433493, 2021). "Post-translational regulation of TGFβ1 signalling is a highly relevant aspect of renal fibrosis." (PMID 34645813, 2021). "Meta-analysis of genome-wide association studies for DKD revealed novel association (P = 1.2 × 10–8) with SNPs in the AFF3 gene, a transcriptional activator that influences renal fibrosis through the TGFβ1 pathway, in individuals who had progressed to end stage renal disease." (PMID 33178681, 2020). "Conclusively, these results suggest that the deletion of Akt1 may contribute to renal fibrosis via induction of the TGFβ1/STAT3 pathway in a murine model of UUO." (PMID 33299873, 2020). "We conclude that renal fibrosis after pyelonephritis is exacerbated by the presence of androgens and involves activation of the TGFβ1 signaling cascade, leading to increases in cortical populations of MSC‐like cells and the Gli1 + activated myofibroblasts that are responsible for scarring." (PMID 32227630, 2020).
renal fibrosis (continued). "Angiotensin II and TGFβ1 have been regarded as major culprits of renal fibrosis in UUO." (PMID 33299873, 2020). "Therefore, LXA4-associated up-regulation of miR-let-7c expression suppresses TGFβ1-induced fibrosis, which is a key pathway that is dysregulated in human renal fibrosis." (PMID 31474862, 2019). "Our results might help to clarify the beneficial role of PPARγ in preventing or reversing TGFβ1-driven renal fibrosis." (PMID 31277592, 2019). "Moreover, sKlotho therapy suppresses renal fibrosis by targeting several fibrotic signaling pathways, including TGFβ-1/Smads and WNT/β-catenin signaling." (PMID 31275449, 2019). "As the dysregulation of the TGFβ1/Smads pathway is central in the progression of renal fibrosis, any intervention that could modulate this pathway should play important roles in the management of the condition." (PMID 31531112, 2019). "Furthermore, the mRNA expression of the renal fibrosis-related genes Col1a2, Fn1, and Tgfb1 were all significantly increased in Pkd1 miR Tg mice (p < 0.05) compared with wild-type mice." (PMID 30585217, 2018). "In this pathway, TGFβ1 mainly transduces its fibrotic signal through activation of TGFβreceptor 1 (TGFβR1) followed by phosphorylation and nuclear translocation of Smad3, thus driving the progress of renal fibrosis." (PMID 30524310, 2018). "However, the only widely accepted fibrogenic signal transduction pathway related to renal fibrosis is the TGFβ1/Smads signal pathway." (PMID 28208683, 2017). "TGFβ1 and TGFβ2 are the major isoforms involved in renal fibrosis." (PMID 28002484, 2016). "Furthermore, our recent in-vivo study showed that P311 promotes renal fibrosis via the TGFβ1/Smad signaling." (PMID 27906099, 2016). "Murine renal fibroblast proliferation and kidney fibrosis following ureteric obstruction were significantly attenuated by KCa3.1 blockers, while in a streptazocin mouse model of diabetes-induced renal fibrosis, KCa3.1 inhibition reduced TGFβ1, TGFBRII and phosphoSmad2/3 expression in the tissue." (PMID 25829947, 2015). "In conclusion, this study demonstrate that P311 plays a key role in renal fibrosis via TGFβ1/Smad signaling, which could be a novel target for the management of renal fibrosis." (PMID 26616407, 2015). "Macrophages are major producers of TGFβ-1, which is crucial to the development of renal fibrosis." (PMID 25300759, 2014). "Therefore, this study evaluated the correlation between the protein expression of TGFβ1 in renal tissue and urine of LN patients with renal fibrosis." (PMID 25279306, 2014). "The role of TGFβ1 in LN and renal fibrosis is still debatable." (PMID 25279306, 2014). "Subjects were 45 patients LN with renal fibrosis and 45 participants without renal fibrosis as control, that were recruited from 2011 to 2013.Their urinary TGFβ1 levels and TGFβ1 gene polymorphisms were examined." (PMID 25279306, 2014). "Levels of urinary and protein expression of TGFβ1 increased in the LN with renal fibrosis group." (PMID 25279306, 2014). "Otherwise, the up regulation of urinary TGFβ1 was not significantly correlated to renal fibrosis but associated with the LN activity." (PMID 25279306, 2014). "The changing of the signal peptide is likely to interfere the transport of TGFβ1 to the endoplasmic reticulum that may affect TGFβ1 production and renal fibrosis." (PMID 25279306, 2014). "TGFB1 in conjunction with Ang II plays a key role in renal fibrosis." (PMID 23404227, 2013). "Many αv integrins play a role in preventing inappropriate vascular growth and controlling vascular permeability, and studies in mice lacking the beta 6 subunit found a role for integrin-mediated TGFβ1 activation in pulmonary and renal fibrosis, acute lung injury, and pulmonary emphysema." (PMID 23547562, 2013).